NLRP3 (NLR family pyrin domain containing 3)
Diseases named in the same sentence as NLRP3 in open-access papers (continued):
Sharing a sentence is not in itself a finding about the gene and the disease.
Arthritis (continued). "Regulatory element of NLRP3-mediated pyroptosis in arthritis." (PMID 37954594, 2023). "ASC deficiency suppresses arthritis in RA model mice through reduced T cell priming, which is independent of NLRP3 or caspase-1." (PMID 35628185, 2022). "Possible explanations for these differences in the results might rely on the mouse background, the protocol and model for arthritis induction, the timing of NLRP3 inhibition, or potential off-target effects of MCC950 in this in vivo model." (PMID 35455985, 2022). "Some of our patients were once misdiagnosed as sJIA for fever and arthritis, and we found that most NLRP3-AID patients didn’t show increased Ferritin, which is usually high in sJIA, and it could be a clue to help clinicians to distinguish those diseases." (PMID 35668534, 2022). "Mice lacking NLRP3 or caspase-1 have reduced joint lesions with spontaneous HA deposition in a progressive ankylosis-deficient model of arthritis." (PMID 35628185, 2022). "Thus, our results revealed a previously unrecognized mechanism whereby gallic acid prevents MSU-induced arthritis by inhibiting the activation of the NLRP3 inflammasome as well as macrophage pyroptosis." (PMID 33365024, 2020). "However, there is very limited evidence that a natural compound targeting NLRP3 inflammasome can exert anti-inflammatory effects on experimental arthritis." (PMID 31200447, 2019). "Correlation analysis showed that the synovial NLRP3 expression might be directly related to the pathogenesis and the disease severity of arthritis." (PMID 27034595, 2016). "Moreover, this is the first study that explored the relationship between the NLRP3 and severity of arthritis from the imaging perspective." (PMID 27034595, 2016). "Our study suggests that NLRP3 is involved in arthritis pathogenesis." (PMID 27034595, 2016). "In this study, we used a mouse model of CIA to investigate the relationship of NLRP3 and arthritis." (PMID 27034595, 2016). "The pathology associated with collagen-induced arthritis triggered by injection of collagen with CFA has been found to be independent of NLRP3." (PMID 26978520, 2016). "This study shows that NLRP3 expression at synovial membranes in the CIA mice significantly increased and is associated with the severity of arthritis, suggesting the involvement of NLRP3 in the pathogenesis of arthritis." (PMID 27034595, 2016). "Animal studies have revisited the role of NLRP3 in the evolution of arthritis." (PMID 26385789, 2015). "We investigated whether deZP could inhibit the NLRP3 inflammasome in a gouty arthritis mouse model." (PMID 39861092, 2024). "Therefore, targeting the NLRP3 inflammasome may provide new therapeutic strategies for treating arthritis." (PMID 36619197, 2022). "Because the activation of the NLRP3 inflammasome could induce the overproduction of IL-1β, resulting in inflammation and arthritis, we evaluated the expression of NLRP3, caspase-1 p20 (a functional caspase-1 subunit) and IL-1β in the ankle joint synovial tissue by Western blot." (PMID 34583676, 2021). "Notably, pathogenicity of disease in these spontaneous arthritis models is complex as, in some cases, disease is rescued by NLRP3 inflammasome deficiency rather than TNF loss, and vice versa." (PMID 33924766, 2021). "Lack of components of the NLRP3 inflammasome prevents the development of neutrophil inflammation in the air-pouch model of synovitis and decreased pathology in the Ank-deficient model of arthritis." (PMID 31520179, 2019). "Thus, hydroxyapatite crystal-induced arthritis may be mediated via NLRP3-independent macrophage death." (PMID 29434606, 2018). "However, other animal models and some human studies also show that NLRP3 may be irrelevant to arthritis." (PMID 27034595, 2016). "In our previous study, we demonstrated that cold exposure can aggravate arthritis via modulating gut microbiota-derived secondary bile acids and the downstream TGR5-cAMP-PKA signaling and NLRP3 inflammasome." (PMID 40375326, 2025).
Arthritis (continued). "In mice, quercetin restores collagen-induced arthritis by inhibiting the TLR-4/NLRP3/p-65 pathway and TH17/Treg balance by hindering NLRP3 signaling." (PMID 39966334, 2025). "Consistent with the in vitro data, these in vivo data suggest that NCOA6 is necessary for NLRP3-dependent inflammatory diseases, including FA-induced ATN and MSU crystal-induced arthritis." (PMID 38195836, 2024). "The main clinical manifestations of NLRP3-AID in our cohort were recurrent urticaria-like rash, arthritis, and periodic fever with increased inflammatory markers." (PMID 38481988, 2024). "Using loss-of-function mouse models, we clearly showed that NCOA6, particularly myeloid NCOA6, has critical functions in promoting NLRP3 inflammasome-mediated inflammatory diseases, including FA-induced ATN and MSU crystal-induced arthritis." (PMID 38195836, 2024). "As for CINCA, it is the severest condition of NLRP3-AID distinguished by chronic severe urticarial-like rash, arthritis fever with significant central nervous system involvement, and distal femur arthropathy." (PMID 38481988, 2024). "MiRNA-20a targets TXNIP to inhibit the activation of NLRP3, ASC and caspase-1 in adjuvant-induced arthritis FLS and to suppress the secretion of IL-1 and MMP-1." (PMID 37426634, 2023). "Suppression of NLRP3 with a highly selective NLRP3 inhibitor, MCC950, was effective in ameliorating arthritis symptoms and cartilage erosion in CIA mice." (PMID 37063906, 2023). "The levels of NLRP3, ASC, and caspase-1 increased in both arthritic rats and patients with arthritis." (PMID 36619197, 2022). "Increased secretion of NLRP3, ASC, and caspase-1 has been reported in arthritis patients, and suppression of NLRP3 activity was reported to suppress arthritis in rat models." (PMID 36619197, 2022). "Wedelolactone can phosphorylate Ser/Thr residues of NLRP3 and inhibit the activity of the NLRP3 inflammasome, thereby inhibiting the occurrence of macrophage pyroptosis and alleviating MSU-induced arthritis." (PMID 35411030, 2022). "Synovial NLRP3 expression is increased in the collagen-induced arthritis (CIA) model, and positively correlates with radiological destruction and arthritis severity." (PMID 35095918, 2021). "NLRP3-AID is characterized by recurrent fever, urticarial rash, and non-infectious inflammation in the central nervous system, accompanied by arthritis/arthralgia, ocular inflammation, and sensorineural deafness." (PMID 34249981, 2021). "Vasculitis is a rare manifestation in patients with NLRP3-AID and is one of the challenging differential diagnoses of NLRP3-AID for they share common features such as intermittent fever, arthritis, cutaneous and ocular involvement." (PMID 34249981, 2021). "In the collagen induced arthritis model, treatment with MCC950, a selective inhibitor of NLRP3, reduces IL-1β, synovial inflammation and cartilage erosion." (PMID 33605409, 2021). "In the TNF-α-stimulated SFs, a significantly lower expression of NLRP3 and TLR4 was observed in the RA group, compared with the other tested forms of arthritis." (PMID 35126351, 2021). "Wedelolactone also exerts an inhibitory effect on NLRP3‐driven inflammation in MSU‐induced peritonitis and arthritis mice." (PMID 32656909, 2020). "Two studies of antigen-induced murine arthritis show dependence on ASC, but caspase-1, NLRP3, and NLRC4 independence." (PMID 32366256, 2020). "In conclusion, the most common clinical manifestations in NLRP3-AID patients were periodic fever of unknown origin, recurrent urticaria-like rash, and arthritis with increased inflammatory markers." (PMID 38481988, 2024). "Since TNF can drive IL-1β secretion via the NLRP3 inflammasome, the role of PAD2 in TNF-induced arthritis may be macrophage-dependent." (PMID 35083342, 2022). "Indeed, there were some similar characteristics of NLRP3-AID and BS, such as recurrent fever, arthritis, and aseptic meningitis leading to headache and dizziness." (PMID 34249981, 2021).
Arthritis (continued). "Mice lacking expression of either NLRP3 or caspase-1 have further been shown to be protected from the induction of experimental arthritis." (PMID 32477105, 2020). "In gout and several other forms of arthritis, nucleotide-binding oligomerization domain-like receptor (NLR) protein 3 (NACHT, LRR and PYD domains-containing protein 3 [NLRP3], cryopyrin) inflammasome activation is critical in both the inflammatory phase and the progression of disease." (PMID 30075804, 2018). "In an antigen-induced arthritis mouse model, NLRP3 inflammasome defect does not affect the incidence of arthritis." (PMID 27034595, 2016). "Activation of the P2X7 receptor and NLRP3-dependent IL-1β production by dendritic cells is important for priming of T cells, and this pathway was shown to regulate CD8+ T cell activity in the anti-cancer immune response and Th17 differentiation in arthritis models." (PMID 33995417, 2021). "NLRP3 may be not the direct binding partner of the compounds, which may bind to various upstream regulators of NLRP3 to regulate the activity of the inflammasome, and, therefore, affect the progression of arthritis." (PMID 39852153, 2025). "However, studies investigating the application of natural products for arthritis treatment via the modulation of the NLR family pyrin domain-containing 3 (NLRP3) inflammasome have not yielded convincing evidence, and studies on Q. serrata in this context are especially rare." (PMID 36619197, 2022). "IL-1β blockade significantly reduced arthritis severity in an antigen-induced arthritis (AIA) mouse model, while Nlrp3 or Nlrc4 gene deletion did not affect AIA." (PMID 35567665, 2022). "However, there is no report on whether NLRP3 is related to the severity of arthritis." (PMID 27034595, 2016). "However, serum NLRP3 expression may not be directly relevant to the arthritis." (PMID 27034595, 2016).
pulmonary fibrosis (151 papers, 2012 to 2025). Chronic progressive interstitial lung disorder characterized by the replacement of the lung tissue by connective tissue, leading to progressive dyspnea, respiratory failure, or right heart failure. "Studies on the genetic polymorphism of pulmonary fibrosis have found that the NLRP3 rs35829419 variant allele is associated with an increased risk of asbestos-related PF." (PMID 40391214, 2025). "NLRP3 activation increases airway resistance, reduces lung compliance, and causes distal lung epithelial remodeling in mice, thus exacerbating pulmonary fibrosis progression." (PMID 40655156, 2025). "Increasing evidence suggests that activation of the NLRP3 inflammasome is closely associated with the progression of pulmonary fibrosis." (PMID 40391214, 2025). "Its role in activating the NLRP3 inflammasome has been implicated in the pathogenesis of conditions such as pulmonary fibrosis, diabetic cardiomyopathy, asthma, radiation-induced brain injury (RIBI), and preterm premature rupture of membranes (PPROM)." (PMID 40788157, 2025). "In pulmonary fibrosis, the NLRP3 inflammasome is implicated in perpetuating inflammation within the lungs." (PMID 38762465, 2024). "Of note, a study also discovered the role of NLRP3 inflammasome activation in EndoMT and lung fibrosis caused by mechanical ventilation." (PMID 37958797, 2023). "In murine silicosis models, deletion of the genes encoding NLRP3 inflammasome components markedly attenuates silica crystal-induced granulomatous lung inflammation and pulmonary fibrosis." (PMID 36131930, 2022). "Deletion of the genes encoding NLRP3 inflammasome components markedly attenuates silica crystal-induced granulomatous lung inflammation and pulmonary fibrosis." (PMID 36131930, 2022). "Identifying the mechanisms underlying the virus-induced NLRP3 inflammasome activation is essential to develop novel therapeutic strategies for lung fibrosis." (PMID 34638790, 2021). "It has also been previously demonstrated that pulmonary fibrosis is closely associated with the activation of NLRP3-inflammasome pathway, production of IL-1β and TIMP-1." (PMID 27247426, 2016). "Importantly, NLRP3 deficiency limits the size of silicotic nodules and overall lung fibrosis, further highlighting the contributions of NLRP3 in promoting hallmark features of silicosis." (PMID 40119408, 2025). "In addition, NLRP3 activation in AT II cells has been linked to pulmonary fibrosis by promoting myofibroblast differentiation from lung-resident mesenchymal stem cells." (PMID 40806699, 2025). "The activation of NLRP3 mediates the downstream inflammatory response, and the overactivation of NLRP3 inflammatory is closely associated with the development of a variety of lung diseases for example the lung injury, pulmonary fibrosis, chronic obstructive pulmonary disease." (PMID 41380328, 2025). "Overexpression of NLRP3 has been reported to cause pulmonary fibrosis." (PMID 38003456, 2023). "Thus, we inferred that NecroX-5 alleviated TGF-β1/Smad2/3 signalling medicated EMT process and pulmonary fibrosis associating with BLM by suppressing NLRP3 inflammasome activation." (PMID 35596212, 2022). "This suggested that NLRP3 inflammasome senses mitochondrial ROS and may explain the frequent association of mitochondrial ROS with pulmonary fibrosis and EMT process." (PMID 35596212, 2022). "The NLRP3 inflammasome, an important part of the innate immune system, has been demonstrated to recognize and respond to danger signals and cause a series of inflammatory responses in many diseases (such as atherosclerosis and pulmonary interstitial fibrosis)." (PMID 34123595, 2021). "Besides, the activation of NLRP3 inflammasome accelerated pulmonary fibrosis caused by airborne fine particulate matter." (PMID 32996690, 2021). "Another study revealed that activation of the NLRP3 inflammasome pathways may contribute to pulmonary fibrosis caused by latent murine cytomegalovirus (MCMV) infection." (PMID 34638790, 2021).
pulmonary fibrosis (continued). "In addition, activation of the NLRP3 inflammasome is known to accelerate pulmonary fibrosis caused by airborne particulate matter." (PMID 34684415, 2021). "While kaempferol’s direct role in NLRP3 inhibition in lung fibrosis remains unstudied, its anti-inflammatory, antifibrotic, and antioxidant properties suggest potential benefits." (PMID 39966334, 2025). "In the IL-33 and LPS/IL-4-induced pulmonary fibrosis cell model, ROS production and mtDNA accumulation, key upstream events of NLRP3 activation in macrophages, were observed, along with a reduction in Nrf2 mRNA levels." (PMID 40391214, 2025). "Studies have demonstrated that carbonaceous particles can induce pulmonary fibrosis through activation of the NLRP3 inflammasome." (PMID 40148858, 2025). "The Exportin 1 (XPO1) inhibitor Selinexor similarly targets GBP5 to suppress the NLRP3 pathway, alleviating pulmonary fibrosis." (PMID 40788157, 2025). "Aberrant activation of the NLRP3 inflammasome has also been detected in animal models of pulmonary fibrosis induced by PM2.5, silica dust, asbestos, and BLM." (PMID 40391214, 2025). "Its antifibrotic effects are particularly notable, as it inhibits NLRP3-associated inflammation and suppresses the PI3K/AKT/mTOR pathway, thereby reducing fibrotic processes in amiodarone-induced pulmonary fibrosis." (PMID 39966334, 2025). "Then, the activated NF-κB upregulates the expression of NLRP3 and IL-1β again, forming a positive feedback loop that triggers an inflammatory cascade, ultimately leading to pulmonary fibrosis." (PMID 40391214, 2025). "We observed that hyperoxia activated the NLRP3 inflammasome, increased macrophage infiltration, and decreased alveolarization and vascular development as well as pulmonary fibrosis in the neonatal lung." (PMID 40486518, 2025). "As the NLRP3 inflammasome is investigated, its role in the progression of pulmonary fibrosis is progressively being elucidated." (PMID 40391214, 2025). "A substantial amount of research indicates that NLRP3 is involved in ER stress within ATII cells during pulmonary fibrosis." (PMID 40391214, 2025). "In summary, saroglitazar attenuates pulmonary fibrosis by suppressing macrophage-driven inflammation via NF-κB/NLRP3 inhibition and disrupting the macrophage–fibroblast crosstalk." (PMID 40731787, 2025). "In the progression of pulmonary fibrosis, various cell types participate in disease development through the NLRP3 inflammasome." (PMID 40391214, 2025). "The following sections will delve into the complex interactions between the NLRP3 inflammasome and various signaling pathways and cellular mechanisms in pulmonary fibrosis." (PMID 40391214, 2025). "Although existing researches have revealed the potential role of NLRP3 in pulmonary fibrosis, many mysteries still remain regarding its specific mechanisms and clinical applications." (PMID 40391214, 2025). "Recent research has found that the NLRP3 inflammasome plays an important role in the pathogenesis of pulmonary fibrosis." (PMID 40391214, 2025). "In an LPS-induced pulmonary fibrosis model, impaired autophagy was observed alongside NLRP3 inflammasome activation." (PMID 40391214, 2025). "Early NLRP3-mediated inflammation preceded later-stage lung fibrosis marked by collagen deposition and the formation of silicotic nodules." (PMID 40119408, 2025). "Purine metabolism also participates in the progression of pulmonary fibrosis through the NLRP3 inflammasome." (PMID 40391214, 2025). "The NLRP3 inflammasome has also been shown to regulate epithelial-mesenchymal transition in the development of pulmonary fibrosis, while HMGB1 promotes fibroblast proliferation and collagen accumulation." (PMID 40688353, 2025). "Inhibition of HMGB1 expression promoted the nuclear translocation of nuclear factor erythroid 2-related factor 2 (NRF2) and enhanced HO-1 levels, thereby reducing NLRP3 expression and partially reversing lung fibrosis." (PMID 40688353, 2025).